TNF (tumor necrosis factor)
Diseases named in the same sentence as TNF in open-access papers (continued):
Sharing a sentence is not in itself a finding about the gene and the disease.
adenocarcinoma (74 papers, 2007 to 2026). A common cancer characterized by the presence of malignant glandular cells. "The TNF-α -238 A allele was associated with borderline higher odds of adenocarcinoma (OR 4.57, 95% CI: 0.95-21.95, p=0.050), while the *IL-1β* -511 T allele appeared protective (OR 0.45, 95% CI: 0.19-1.07, p=0.049)." (PMID 41727446, 2026). "To investigate the effect of 1,8-cineole on human colonic cells, we employed HT-29 adenocarcinoma cells challenged with TNF-α to provide an in vitro model of colonic inflammation." (PMID 37047133, 2023). "Markers such as TNFα, IL-6, and Ataxin-10 were observed to be elevated in cardiac tissue of colon-26 (C26) adenocarcinoma mice." (PMID 35326491, 2022). "TNF-α challenged HT-29 adenocarcinoma cells is a well-accepted in vitro model system for human colon epithelial inflammation." (PMID 35465355, 2022). "β-myrcene also suppressed mRNA expression of proinflammatory chemokines in tumor necrosis factor-α (TNF-α) challenged HT-29 adenocarcinoma cells." (PMID 36557879, 2022). "TNF-α stimulated HT-29 adenocarcinoma cells, a well-accepted in vitro model for human colon epithelial inflammation." (PMID 33920708, 2021). "But the tumor necrosis factor mostly increases only in moderately and low differentiated adenocarcinomas." (PMID 32963755, 2020). "Our data show that TNF is more elevated in patients with moderate- and low-differentiated adenocarcinoma." (PMID 32963755, 2020). "They showed a significant reduction in aberrant crypt foci formation and adenocarcinoma count along with a significant (p<0.05) reduction in TNF-α levels as compared to DMH control at 100 mg/kg dose." (PMID 28694750, 2017). "Cultured HT-29 adenocarcinoma cells treated with a combination of tumor necrosis factor-α (TNF-α) and sodium butyrate exhibited reduced interleukin-8 (IL-8) secretion in comparison to cells treated with TNF-α alone." (PMID 29231905, 2017). "H-SN1 was also shown to suppress TNFR1–associated signaling pathways as it minimized TNF-α-induced NF-кB and MAPK activation in HEK293 embryonic kidney and HT29 adenocarcinoma cell lines." (PMID 27158082, 2016). "To examine the inhibitory effect of the two drugs in an additional cellular model of programmed necrosis, we treated human adenocarcinoma HT-29 cells with TNF-α in presence of the Smac mimetic birinapant, and the pan-caspase inhibitor z-VAD-FMK." (PMID 25996294, 2015). "AOM augments the expression of cyclooxygenase- (COX-) 2 and consequently prostaglandin E2 (PGE2) levels within adenocarcinomas and upregulates a number of proinflammatory cytokines, including tumor necrosis factor- (TNF-) a and interleukin-1a/b." (PMID 26504896, 2015). "In a long-term study (8 months) of rats, the highest levels of IL-4 and TNF-α were found in the groups that showed the lowest numbers of adenocarcinomas in response to DMH induction." (PMID 19660118, 2009). "Finally, the potential anti-inflammatory effect of FeMF and MF was evaluated on human adenocarcinoma cell line (HT-29) exposed to TNF-α inflammatory stimulus." (PMID 38472817, 2024). "NF-κB mediates apoptosis in adenocarcinoma cells infected with retrovirus or treated with TNF-α." (PMID 36770846, 2023). "These three compounds might also increase anoikis-induced cells in adenocarcinoma because anti-inflammatory and anti-oxidative responses particularly accompanied the down-regulation of NFκB, TNFα and NRF2, the key pathways for anoikis." (PMID 31905803, 2019). "In the present study, it was revealed that F. nucleatum could induce the production of proinflammatory cytokines (IL-8, IL-1β and TNF-α) and reactive oxygen species (ROS) in Caco-2 colorectal) adenocarcinoma cells." (PMID 27828984, 2016). "To determine the extent to which off-target effects generated “hit” phenotypes in our primary screen, we performed a validation screen where we tested each individual siRNA alone for modification of NF-κB responses to TNF in HeLa cells and adenocarcinoma A549 cells." (PMID 25071782, 2014).
adenocarcinoma (continued). "Because the same localization pattern was noted for TNF-α mRNA in the four cases, and also that the four cases showed the similar miR-21 localization pattern, we assume that our findings are representative for such adenocarcinomas despite the limited number of cases." (PMID 30999696, 2019). "Consistent with our findings, a transgenic adenocarcinoma of mouse prostrate (TRAMP) model has demonstrated that oral administration of piceatannol, derived from PFBE, reduced TNF-α levels in the liver of mice." (PMID 40426961, 2025). "Inasmuch as TNFα-NFκB pathway was enriched in KEAP1 R320 and R470 adenocarcinoma samples in our GSEA analysis, we analyzed the expression of two NFκB target genes, IL23A and BIRC2, in transduced cells." (PMID 38184997, 2024). "4’-geranyloxy-ferulic acid and auraptene, both natural compounds isolated from plants, enhanced apoptosis in adenocarcinoma in AOM/DSS mice through suppression of NFκB, TNFα, NRF2, IL-6 and IL-1β." (PMID 31905803, 2019). "We measured the concentration of IL-6, IL-10, TNF-α, MCP-1, INF-γ, and IL-12p70 secreted in the conditioned medium (CM) by the murine colon C-26 adenocarcinoma cells." (PMID 24967341, 2014). "The exception for this compound compared to TNF-α is that no significant NFkB activation was observed in treated HT-29 adenocarcinoma cells." (PMID 27070314, 2016). "Moreover, Wilson and Browning (2002) showed that TNF induces apoptosis and necrosis simultaneously in the HT29 adenocarcinoma cells." (PMID 24759995, 2014). "Moreover, it has been shown that murine SAA3 recombinantly expressed in E. coli (mu rSAA3) induces tumor necrosis factor-α (TNF-α) mRNA in peritoneal macrophages and murine colonic CMT-93 cells and matrix metalloproteinases (MMPs) and CCL5 mRNA in murine adenocarcinoma VMR cells." (PMID 32694927, 2020). "Tumor necrosis factor-α (TNF-α), for example, is a proinflammatory cytokine secreted by macrophages in acute inflammatory response, and during sustained inflammation TNF-α level within colonic mucosa is increased, which contributes to the invasiveness of adenocarcinomas." (PMID 26910375, 2016). "The unstimulated group had low levels of TNFα and IL10, however, upon stimulation, we saw an additional in vitro release of TNFα and IL10 in both groups, but the release was not different in samples of patients with adenocarcinoma." (PMID 37610509, 2023).
retinopathy (72 papers, 2004 to 2025). "Previously in an oxygen-induced retinopathy model we found that genetic deficiency of RORα regulates macrophage polarization and retinal inflammation with dampened TNFα." (PMID 36626253, 2023). "Elevated TNFα level was found to be associated with severe retinopathy in T1DM patients with kidney disease; however, at a 15‐year follow‐up, this correlation was no longer observed." (PMID 34269526, 2022). "Circulating TNFα levels have been associated with retinopathy in several studies on patients with both T1DM and T2DM." (PMID 34269526, 2022). "Together, these studies show a clear role for NFAT-signaling in TNFα-induced retinal leukostasis, and identify NFATc2 and NFATc4 as potentially valuable therapeutic targets for treating retinopathies in which TNFα plays a pathogenic role." (PMID 26527057, 2015). "Loss of insulin signaling through insulin resistance, loss of β2-adrenergic receptor input, and production of the anti-apoptotic inhibitors, TNFα, could lead to retinal cell death associated with retinopathy." (PMID 23894672, 2013). "A meta-analysis of aqueous humor and vitreous cytokines in patients with retinopathy showed significantly higher levels of TNF-α and VEGF-A than in normal subjects." (PMID 41567638, 2025). "The inflammatory response in retinopathy is manifested as the overexpression of various inflammatory factors, such as tumor necrosis factor-α (TNF-α), interleukin-6 (IL-6), and cyclooxygenase-2 (COX-2)." (PMID 40717982, 2025). "As the disease progressed, TNFα production doubled and was correlated with the severity of retinopathy." (PMID 38842591, 2024). "TNF inhibitors, with their anti-inflammatory effects, positively impact diabetic complications by reducing the incidence of retinopathy." (PMID 38842591, 2024). "Altogether, here we characterized the gene expression profiles of AAV-VEGF, TNF-α, or IL-6 driven retinopathy mouse models, and combined these measurements with publicly available singe-cell RNA expression data." (PMID 36371417, 2022). "Various pre-clinical rodent models have directly or indirectly shed light on the function of VEGF, TNF-α, or IL-6 in retinopathies." (PMID 36371417, 2022). "Altogether, our study represents a valuable investigation of gene expression changes induced by VEGF, TNF-α, and IL-6 and will aid researchers in selecting appropriate animal models for retinopathies based on their agreement with the human pathophysiology." (PMID 36371417, 2022). "TNF-α levels have been increased in animal models of proliferative retinopathy due to retinal neovascularization." (PMID 35778716, 2022). "Upregulation of various proinflammatory cytokines, including TNF, has been reported in the vitreous/aqueous samples of diabetic patients with retinopathy." (PMID 35692536, 2022). "In summary, the long-term expression of human VEGF-A165, TNF-α, or IL-6 in the mouse eye induced specific pathologies within 6 weeks that mimic different aspects of human retinopathies." (PMID 34520511, 2021). "Using another experimental paradigm, the mouse model of oxygen-induced retinopathy, our group detected only minor changes in the TNF-Rpd mice compared to wild-type controls." (PMID 33835999, 2021). "Pioglitazone improved retinopathy in mice models through decreasing inflammation and neovascularisation in the retina in diabetic mice by decreasing TNF-alpha through stimulation of adiponectin, a known natural anti-inflammatory mediator." (PMID 34233552, 2021). "Connoret al. used a hypoxia-induced animal model of retinopathy to show that an omega-3 PUFA diet suppressed retinal expression of the inflammatory cytokine tumour necrosis factor (TNF)-α and macrophage-induced inflammatory responses in retinal cells." (PMID 33145006, 2019). "TNF-a and VEGF have received particular attention for their role in the vascular lesion and neovascularization associated with late stage retinopathy." (PMID 30618774, 2018).
retinopathy (continued). "In retinopathy models, mRNA expression of the inflammatory cytokines IL-1β and TNFα, as well as Sema3a, increased significantly compared to controls." (PMID 29975739, 2018). "Blocking the activity of pro-inflammatory cytokines (such as TNF-α, IL-6, and IL-1) has shown beneficial effects in models of retinopathy." (PMID 30618774, 2018). "Serum levels of IL-6 and TNF- α are proposed to be predictor of proliferative retinopathy development." (PMID 19784389, 2009). "It has been reported that TNF-α is expressed and up-regulated in human retinas with proliferative retinopathy." (PMID 19823583, 2009). "Recently, we have shown that type 1 diabetic patients with proliferative retinopathy have increased levels of TNF- α." (PMID 18575614, 2008). "Allelic association of LTA T60N (C→A), TNF -308G→A and AGER -374 T→A polymorphism with diabetic nephropathy, retinopathy and macrovascular complications." (PMID 18575614, 2008). "Variation in TNF and LTA genes has been associated with diabetic nephropathy, retinopathy as well as with cardiovascular and cerebrovascular disease." (PMID 18575614, 2008). "The hyperoxia induces liberation of TNF with a powerful inflammatory action; dexamethasone interferes with TNF production attenuating the manifestations of retinopathy by hyperoxia." (PMID 15298714, 2004). "Cytokines that mainly seem to play a role in the development of retinopathy in DM are the pro-inflammatory cytokines interleukin-1β (IL-1β), IL-6, and tumor necrosis factor (TNF)-α, as well as the chemokine IL-8 as these are elevated in vitreous samples from PDR patients." (PMID 36662891, 2023). "Tumor necrosis factor alpha (TNF-α) is a well-known proinflammatory cytokine that is described as a biomarker for inflammation in diverse retinopathies and therefore emerged as an interesting target to treat inflammation in the eye by neutralizing anti-TNF-α antibodies." (PMID 35579886, 2022). "This is also supported by our interpretation of the potential mechanism whereby systemic TNF-α causes the tissue RAS activation in the diabetic retina; therefore, blocking intraocular TNF-α only topically was likely to be insufficient in suppressing the activity of retinopathy." (PMID 29240802, 2017). "Intraocular injection of TNFα leads to increased leukocyte adhesion to the vascular endothelium, and provides an acute model for a pathological feature of retinopathy that may take months or years to develop in diabetics." (PMID 26527057, 2015). "Our work has suggested that additional TNFα pathways may also be involved in apoptosis related to retinopathy." (PMID 25073020, 2014). "Remarkably, TNF-α stimulation strongly increased Madcam1 expression in HRMECs, suggesting that MAdCAM-1 may play an important role also in the human retina and may contribute to disease progression of various human retinopathies." (PMID 36371417, 2022). "For example, a flow-chamber-based adhesion assay was established to measure TNF-α–induced increased monocyte adhesion to retinal vascular endothelial cells indicating that retinal vascular cells may be used in cell adhesion assays to study retinopathies." (PMID 35579886, 2022). "Further, the authors found that the increased vitreous levels of sTNF-Rs correlate with the degree of retinopathy severity and posit that effective control of TNF-α activity by sTNF-Rs within the retinal microenvironment may determine the outcome and severity of retinal proliferative conditions." (PMID 23028203, 2012). "This study will furnish a significant theoretical foundation for the utilization of TNF-α and VEGF-A as therapeutic targets in DR and for the treatment of retinopathy via non-invasive administration of nanobodies." (PMID 41567638, 2025). "They decreased the expression of IL-6 and TNF-α and the production of iNOS, while anti-inflammatory IL-10 was upregulated both in hypoxia-treated BV2 cells and a retinopathy mouse model through inhibition of the NF-κB pathway." (PMID 36768783, 2023).
retinopathy (continued). "Serums TNF-α and IL-1β are significantly elevated in patients with T2DM retinopathy and gradually increase with disease progression." (PMID 35979044, 2022). "The degree of retinopathy was evaluated by staining retinal sections with hematoxylin and eosin, and the expression of CCN1, HIF-1α, VEGF, caspase-3, Bcl-2, IL-1β, and TNF-α protein was analyzed by Western blotting and immunohistochemistry." (PMID 35445044, 2022). "Cytokines and growth factors including TNFα, IL-6, MCP1, and VEGF are upregulated in the vitreous of patients with proliferative retinopathy, and have been shown to mediate pathological neovascularization in OIR." (PMID 36038541, 2022). "In the studies reported here, we further examine the link between TNFα and IGFBP-3 cascades and the ways in which they interact to create conditions of retinopathy." (PMID 25073020, 2014). "IL-4 and TNF were also significantly increased in this group compared to the T2D without retinopathy group." (PMID 35692536, 2022). "Altogether, we present in this study how TNF-α induced retinal inflammation may be studied both in an AAV-TNF-α driven in vivo model and in vitro cell cultures to further understand the function of TNF-α in retinopathies." (PMID 35579886, 2022). "PDR patients also demonstrated significant upregulations of TNF-α and IL-6 in the VH when compared to the vitreous of non-diabetic patients without retinopathy." (PMID 29695738, 2018). "The NPDR children demonstrated a significantly longer duration of the disease in addition to higher HbA1c, albumin excretion rate, C-reactive protein, systolic blood pressure, as well as TNF-α and IL-6 levels than those without retinopathy." (PMID 17641733, 2007). "Children without retinopathy were characterized by significantly higher TNF-α, IL-6, as well as IL-12 serum levels in relation to the healthy controls." (PMID 17641733, 2007). "As many as 76% of the NPDR children had a detectable serum level of TNF-α while in the group without retinopathy only 34% were TNF-α positive." (PMID 17641733, 2007). "Unfortunately, due to the limited number of patients treated with each anti-TNF agent, we could not demonstrate their effects on glucose levels and the incidence of retinopathy separately." (PMID 38842591, 2024). "Thus, to test whether MAdCAM-1 may also be relevant for human retinopathies, we stimulated primary human retinal microvascular endothelial cells (HRMEC) with recombinant, human TNF-α." (PMID 36371417, 2022). "IL-2, IL-10, IL-12, IFN-α, and TNF-α were unmeasurable in significantly more diabetic samples, and where measurable, the median levels were significantly lower in diabetic patients with and without retinopathy compared to non-diabetics." (PMID 22511846, 2012). "For example, elevated levels of tumor necrosis factor (TNF)-α, interleukin (IL)-8, and soluble IL-2 receptors were found in the serum of diabetic patients; increased vitreous concentrations of IL-6 and IL-8 were also found in patients with proliferative retinopathy." (PMID 22312190, 2012). "Vitreous concentrations of IL-6 and IL-8 were significantly greater in patients with PDR than in noninflammatory retinopathies, and serum TNF-α was significantly greater in PDR than in noninflammatory retinopathies (this latter finding was limited to the serum but did not hold true in the vitreous)." (PMID 23028203, 2012). "Therefore, the aim of our study was to investigate the effect of Cs-A on the retinopathy in a type 2 DM animal model and to elucidate its potential mechanism, specifically, to study the alternation of expression levels of HMGB-1, IL-1β and TNF-α in the retinal tissues." (PMID 32019593, 2020). "In the EURODIAB prospective complications study, circulating IL‐6, in combination with C‐reactive protein and TNFα, was able to stratify T1DM patients with no retinopathy, NPDR and PDR." (PMID 34269526, 2022). "TNF-α was detectable in 76% of the NPDR children and only in 34% ofthe DM type 1 children without retinopathy." (PMID 17641733, 2007).
retinopathy (continued). "The serum levels of TNF-α and IL-6 in the group with NPDR were significantly higher as compared with children without retinopathy." (PMID 17641733, 2007).